UBE2C (ubiquitin conjugating enzyme E2 C)
Diseases named in the same sentence as UBE2C in open-access papers (continued):
Sharing a sentence is not in itself a finding about the gene and the disease.
cancer (continued). "Overexpression of UBE2C is associated with tumorigenesis and tumor progression in various types of cancer." (PMID 32899896, 2020). "We validated junctions from the cancer-associated genes UBE2C (chr20:44443109–44444493), and TGFBI (chr5:135390550–135390958) which were confirmed by the Integrative Genomics Viewer (IGV) using raw RNA-Seq data." (PMID 32437477, 2020). "Overexpression of UBE2C causes chromosome mis-segregation, a loss of genomic stability, and alterations of the cell cycle profile, which are the typical characteristics of cancer." (PMID 33396624, 2020). "In conclusion, our study reported that UBE2C expression was associated with cell growth, invasion/migration and cancer stemness in TSCC." (PMID 32899896, 2020). "Cells overexpressing Ube2c ignore the mitotic spindle checkpoint signals and lose genomic stability, which is a hallmark of cancer." (PMID 30284595, 2019). "We found that SMARCB1 deficient cancer cell lines required UBE2C, an ubiquitin-conjugating enzyme, for survival." (PMID 30860482, 2019). "In BC, high UBE2C expression is associated with a poor prognosis after radical cystectomy, and with higher tumor stage, lymphovascular invasion, and shorter cancer-specific survival." (PMID 27528424, 2016). "UBe2c was established to be associated with growth and apoptosis inhibition in cancer cells, thus playing a role in tumorigenesis and showing potential to be a biomarker of both diagnosis and prognosis." (PMID 24376604, 2013). "The UBE2C gene is localized to 20q13.1, a chromosomal region frequently associated with genomic amplification in many types of cancers." (PMID 23587173, 2013). "The UBE2C immunostaining was observed essentially in the nuclei of the carcinoma cells; however, in some cases, it was associated with a cytoplasmic immunostaining." (PMID 19513072, 2009). "Consequently, the association of UBE2C with immunotherapy suggests its potential as an immunotherapeutic target in the context of these 20 cancer types." (PMID 38577722, 2024). "Although UBE2C overexpression has been linked to immune cell infiltration in various cancer types, it may differ depending on the cancer type and require further investigation." (PMID 38577722, 2024). "Furthermore, UBE2C has been identified as a potential diagnostic and therapeutic biomarker, as well as a prognostic signature for various cancers." (PMID 38577722, 2024). "However, the detailed mechanism of UBE2C in promoting cancer progression, as well as its specific diagnostic, prognostic, and immunotherapeutic value in LUAD, have not been extensively studied." (PMID 38370368, 2024). "Similarly, KIF4A, ZWINT, and UBE2C are involved in cell cycle regulation, cell proliferation, and mitosis, with frequent dysregulation observed in cancers and a clear association with tumor progression and poor clinical outcomes." (PMID 39684488, 2024). "Notably, cells exhibiting UBE2C overexpression display a disregard for mitotic spindle checkpoint signals, resulting in compromised genomic stability—a hallmark characteristic of cancer." (PMID 38894657, 2024). "All these findings suggest that UBE2C is closely associated with the development of cancer and could be a potential therapeutic target for different types of cancers." (PMID 37958642, 2023). "TOP2A, CENPF, TROAP, CDC20, CDCA5, and UBE2C are all reported to be associated with cancer." (PMID 36932399, 2023). "Notably, the strong concordance between our transcriptomic screening using polyploid Huh7 cells and bulk RNA sequencing of genome-duplicated pan-cancers suggests that the expression of UBE2C is robustly associated with polyploidy in cancers." (PMID 37715023, 2023). "UBE2C overexpressing cells have the ability to override mitotic spindle checkpoints, which may lead to loss of genomic stability, a characteristic of cancer." (PMID 37377594, 2023).
cancer (continued). "All these findings suggested that UBE2C is closely associated with the development of cancer, and could be used as a potential therapeutic target for different types of cancers." (PMID 36292703, 2022). "In addition, the hypermethylation level of UBE2C in cancers was associated with better follow-up survival in KIRC and KIPR." (PMID 35804892, 2022). "Moreover, the survival analyses revealed that the high expression of UBE2C was significantly associated with a poor prognosis in patients of nine cancer types." (PMID 36292703, 2022). "The UBE2C-encoded protein is involved in mitotic cyclin destructions and cell cycle progression; hence, it potentially could participate in cancer development." (PMID 35124721, 2022). "In summary, the systematic analysis of UBE2C revealed that it might be a diagnostic and therapeutic biomarker across many cancers." (PMID 34950739, 2021). "The TISIDB tool analysis showed that UBE2C expression was positively associated with the 28 tumor-infiltrating lymphocytes, 45 immune stimulators, 24 immune inhibitors, 41 chemokines, 18 receptors, and 21 MHCs in different cancer types." (PMID 34858987, 2021). "Moreover, excess Ube2C increases sporadic tumour formation in mice and over-expression of Ube2C is associated with various human cancers." (PMID 34186008, 2021). "In total, UBE2C could be remarkably associated with cancer development and a potential biomarker for pan-cancer." (PMID 34950739, 2021). "Among these, UBE2C has been demonstrated to be a high tumor marker associated with advanced cancer." (PMID 34445467, 2021). "Therefore, overexpression of UBE2C contributes to increased cell proliferation, and as a result, cancer cells acquire a hallmark of tumorigenicity through uncontrolled cell proliferation." (PMID 23587173, 2013). "Finally, the UBE2C protein network shows strong associations with cancer-related proteins involved in the formation and maintenance of the mitotic spindle, chromosome segregation, microtubule depolarization, centrosome integrity, and homologous recombination and repair of DNA in different cancers." (PMID 37958776, 2023). "Therefore, UBE2C might be associated with immunotherapy and might be an immunotherapeutic target in these 20 cancer types." (PMID 34950739, 2021). "In our study, using various public databases, such as GEO, CCLE, GEPIA, UALCAN, TIMER, and Oncomine, we found that UBE2C was upregulated in different human cancers, and high expression of UBE2C was significantly associated with tumor stage and lymph node metastasis of various cancers." (PMID 34858987, 2021). "In addition, high expression of UBE2C was associated with poor prognosis of human cancer." (PMID 34858987, 2021). "In particular, UBE2C silencing and gene knockdown experiments in cancer models have consistently demonstrated its pivotal role in tumour progression and cell cycle regulation, thus validating this enzyme as a valuable drug target." (PMID 41492994, 2026). "UBE2C (also known as UbcH10) is a ubiquitin-conjugating enzyme essential for mitotic progression and a potential therapeutic target in cancer." (PMID 41492994, 2026). "Subsequently, we selected PILRA, MKI67, and UBE2C, which were significantly upregulated in both cancer types, for further validation using immunohistochemistry." (PMID 41328437, 2025). "UBE2C, an E2 ubiquitin-conjugating enzyme, is widely recognized for its role in tumor progression and poor prognosis across various cancers." (PMID 41328437, 2025). "Among these, PILRA, MKI67, and UBE2C showed consistently elevated expression in both cancers and were validated through RT-qPCR and immunohistochemistry, suggesting their potential as therapeutic targets." (PMID 41328437, 2025). "The two marker FDGs in HDFM, CDC20 and UBE2C had been previously reported to have a strong correlation in 27 cancers." (PMID 38462627, 2024). "As well, the result showed that significant high protein expression levels of UBE2C protein in 20 different cancer type increase." (PMID 38577722, 2024).
cancer (continued). "CDCA3 correlation with UBE2C across all TCGA cancers highlights its potential significance in diverse contexts." (PMID 38577722, 2024). "Pan-cancer assay shown that UBE2C was significantly overexpressed in 28 cancers and was correlated with Ki-67 index in many cancers." (PMID 38370368, 2024). "Pan‐cancer analysis was performed to compare expression levels of the UBE2C gene between tumor and normal tissues." (PMID 38577722, 2024). "Similar to CDC20, overexpression of UBE2C has been observed in different cancers, fueling cancer cell proliferation." (PMID 38462627, 2024). "The GEPIA2 database was utilized to analyze the expression of UBE2C in various cancer types and normal tissues." (PMID 38370368, 2024). "Ubiquitin-conjugating enzyme 2C (UBE2C) is involved in many cellular processes and the tumour progression of various cancers." (PMID 39234248, 2024). "To study UBE2C protein expression levels in different types of cancer, we used the CPTAC and HPA databases." (PMID 38577722, 2024). "The high expression of UBE2C gene always occurs in cancers with a high degree of malignancy, low differentiation, and high metastatic tendency." (PMID 38741183, 2024). "Acting as an oncogene in these cancers, UBE2C plays a crucial role in both cancer development and therapy, suggesting its potential as an effective therapeutic target for pan‐cancer." (PMID 38577722, 2024). "Ubiquitin-conjugation enzyme E2C (UBE2C) is a crucial component of the ubiquitin-proteasome system that is involved in numerous cancers." (PMID 38690615, 2024). "A comprehensive pan‐cancer analysis of UBE2C expression in a wide array of tumors revealed that UBE2C is upregulated in 28 different cancers, which is in alignment with earlier findings as stated in previous reports." (PMID 38577722, 2024). "In the current study, pan cancer analysis identified UBE2C as a common DEG nearly among all types of cancer, which was correlated with poor prognosis and have a crucial diagnostic value in many cancer types." (PMID 38577722, 2024). "Our findings revealed that UBE2C was positively correlated with the levels of Th2 infiltration in 33 types of cancers, with the exception of UCS." (PMID 38370368, 2024). "Previous studies showed that the UBE2C expression level involved in cancer progression and invasion." (PMID 38577722, 2024). "Knockdown of UBE2C in cancer cells enhanced autophagy and increased apoptosis, while overexpression of UBE2C promoted tumor growth in a mouse model." (PMID 39403142, 2024). "Ubiquitin conjugating enzyme E2C (UBE2C) has been proven to be a pro-cancer factor in multiple studies." (PMID 38556560, 2024). "UBE2C expression levels were positively associated with immunocyte infiltration, immune regulatory genes, immune checkpoints, TMB, MSI and MMRs in some cancers." (PMID 38370368, 2024). "Previous studies have extensively reported the involvement of UBE2C in cancer through the Akt/mTOR signalling pathway." (PMID 38690615, 2024). "Overall, our study validated UBE2C as a promising biomarker for cancer diagnosis and prognosis, as well as a target for cancer therapy." (PMID 38370368, 2024). "In most of the cancers, there was a significant correlation between UBE2C gene expression and HLA‐DMB, HLA‐DOA, HLA‐DPA1, HLA‐PDB1, HLA‐DRA, and HLA‐E." (PMID 38577722, 2024). "In recent years, several studies have demonstrated that UBE2C exhibits high expression in a variety of malignant tumors." (PMID 39334908, 2024). "In this study, there was a significant correlation between UBE2C expression and most of the immune cells by pan‐cancer analysis." (PMID 38577722, 2024).
cancer (continued). "In a pan-cancer analysis, it was found that UBE2C is up-regulated and its expression is correlated with cancer progression, poor prognosis, tumor stage, and lymph node metastasis." (PMID 38075202, 2024). "Previous studies confirmed that UBE2C plays an important role in various malignancies and affects cancers through the PI3K/Akt/mTOR signaling pathways." (PMID 38690615, 2024). "The PI3K/AKT/mTOR/signaling pathway has been correlated with UBE2C levels in several cancers, including thyroid, gastric, and pancreatic cancer." (PMID 37958776, 2023). "As important components of the cell cycle, high levels of UBE2C and PLK1 are commonly associated with aggressive cancers and poor patient prognoses for multiple cancer types." (PMID 37958642, 2023). "More importantly, many studies have indicated that UBE2C also plays an essential role in the progression of different cancer types." (PMID 38102624, 2023). "It has previously been shown that in cancer cells UBE2C plays an important role in facilitation of protein degradation and dysregulation of the cell cycle." (PMID 37377594, 2023). "Using UBE2C as the query gene and UCEC as the CPTAC dataset, the UBE2C proteomic expression profiles based on sample types, individual cancer stages, patient’s age, weight, race, tumor grade, and tumor histology were depicted." (PMID 37803076, 2023). "When we analysed the cancer-specific genes like Cdc20, Hmmr, Tpx2, Cenpf, Birc5, Ube2c, Foxm1,Pold4, Nup210, Cenpm and Orc1, these pro-carcinogenic genes found to be over expressed in the disease control group." (PMID 36650455, 2023). "The genetic alterations and PTMs of UBE2C gene were analyzed in all the different cancers available in the cBioPortal database." (PMID 37803076, 2023). "In the last years, growing data have been exhibiting the human ubiquitin-conjugating enzyme E2C (UBE2C) as a relevant player in tumorigenesis and a valuable biomarker in several types of cancers." (PMID 37958776, 2023). "To study the effect of UBE2C in cancer cell migration, we performed real-time cell analyses using the xCELLigence system." (PMID 37215954, 2023). "Transcriptional and epigenetic regulators, such as transcription factors and micro RNAs, have been identified to regulate UBE2C in cancers." (PMID 36765911, 2023). "As UBE2C is commonly upregulated in multiple cancers, inhibition of this gene has been explored, however inhibitors specifically for this protein are not widely used in the clinic." (PMID 36937454, 2023). "Previous studies suggest that ubiquitin-conjugating enzyme E2C (UBE2C) serves as an oncogene in human cancers." (PMID 37580802, 2023). "Early cancer treatment with dactolisib (dual PI3K/mTOR inhibitor) prevented the development of UBE2C-induced leptomeningeal metastases." (PMID 37215954, 2023). "For example, ectopic UBE2C overexpression promoted, whereas UBE2C knockdown inhibited, cell proliferation in various cancer cell lines." (PMID 36548081, 2023). "Previous studies have revealed that the interference of UBE2C inhibits the growth of cancer cells and blocks the G2/M transition, triggering apoptosis." (PMID 37958642, 2023). "We performed a correlation analysis in tumor tissue samples across 33 cancer types, which showed that the correlation coefficient between UBE2C and BIRC5 was 0.23–0.94." (PMID 37958642, 2023). "As a member of the E2 ubiquitin-conjugating enzyme family, UBE2C is overexpressed in all 27 cancers, and patients with higher UBE2C expression levels exhibited a shorter overall survival duration." (PMID 37508365, 2023). "UBE2C functions as a critical regulator of multiple biological processes and its dysregulation appears in many human cancers, including melanoma, gastric cancer, non-small cell lung cancer, rectal cancer and esophageal squamous cell carcinoma." (PMID 37580802, 2023).
cancer (continued). "Human cancers with higher levels of UBE2C exhibit increased aggressiveness, low differentiation, and metastatic predisposition and are associated with reduced patient survival." (PMID 37958776, 2023). "In other cancers, both nuclear and cytoplasmic UBE2C immunoreactivity have been observed, but the functional significance of this is unclear." (PMID 37377594, 2023). "UBE2C showed significantly higher mRNA levels in stage 2, 3, 4 versus stage 1, indicating its potential role in cancer progression." (PMID 37803076, 2023). "Ubiquitin-conjugating enzymes E2S (UBE2S) and E2C (UBE2C) are important members of the E2 family and were reported to play oncogenic roles in the tumorigenesis and progression of many cancers." (PMID 36860312, 2023). "UBE2C has been described as a promoter of migration and invasion of tumor cells in several other types of cancer." (PMID 37958776, 2023). "Another recent study using single-cell RNA sequencing in human BM from diverse cancer types identified UBE2C as a signature gene in the proliferative molecular subgroup." (PMID 37958776, 2023). "In orthotopic mouse models of BM, UBE2C promoted leptomeningeal dissemination and decreased survival, possibly due to an increase in cancer cell migration and invasion." (PMID 37215954, 2023). "Further studies are warranted to better explore the mechanisms of UBE2C-driven dissemination to the brain and to dissect the cellular interplay between cancer, stroma, and immune cells, mediated by UBE2C." (PMID 37215954, 2023). "E2 enzymes are abnormally translated in a variety of cancers, being responsible for tumor progression and unfavorable biological and clinical characteristics, which emphasizes the relevance of UBE2C as a potential therapeutic target." (PMID 37958776, 2023). "The data described in the present study showed that the combined inhibition UBE2C and PLK1 or BIRC5 caused a decrease in the mRNA expression of ACLY, suggesting a possible novel strategy for cancer therapy." (PMID 37958642, 2023). "Given the promising role of ubiquitin system as a target of new cancer treatments, the role and function of UBE2C in HB progression should be investigated further." (PMID 37377594, 2023). "Ubiquitin-conjugating enzymes E2S (UBE2S) and E2C (UBE2C), which mediate the biological process of ubiquitination, have been widely reported in various cancers." (PMID 36860312, 2023). "The result demonstrated that UBE2C protein level was significantly upregulated in ccRCC compared to par-carcinoma tissue, which was consistent with previous result from CPTAC." (PMID 37056778, 2023). "We also conducted immunohistochemistry (IHC) staining to investigate the UBE2C protein level in ccRCC and par-carcinoma tissue." (PMID 37056778, 2023). "UBE2C, being a member of the E2 family, has a positive correlation with cancer grades and the quality of outcome in various cancers." (PMID 35945960, 2022). "Previous evidence has indicated that UBE2C possessed an oncogenic property and the mRNA and/or protein expressions of UBE2C were abnormally upregulated in a wide range of human cancers." (PMID 35332135, 2022). "Ube2c overexpression has been detected in various cancers, such as hepatocellular carcinoma, esophageal cancer, and breast cancers." (PMID 36499442, 2022). "As a marker gene of Epi-C6, investigating the UBE2C gene is very important for us to further understand the role of UBE2C + cancer cells (Epi-C6)." (PMID 36434043, 2022). "In conclusion, these findings indicate that the process of AIS to MIA is a confirmed key step for LUAD invasion, and the UBE2C + cancer cell subpopulation was found to play a vital role in driving this process." (PMID 36434043, 2022).